LEP (leptin)
Diseases named in the same sentence as LEP in open-access papers (continued):
Sharing a sentence is not in itself a finding about the gene and the disease.
Dyskinesia (2 papers, 2023 to 2025). A movement disorder which consists of effects including diminished voluntary movements and the presence of involuntary movements. "In the presented study, a correlation between plasma leptin levels in the PD patients and disease progression in the form of dyskinesia was determined." (PMID 37233709, 2023). "The level of leptin was increased both in ES (p < 0.001) and AS (p < 0.001) versus CG, while resistin was increased only in patients with dyskinesia (p < 0.05)." (PMID 37233709, 2023). "Moreover, resistin concentrations were statistically significant increased, whereas leptin level was decreased in the dyskinesia PD patients versus the control group." (PMID 37233709, 2023). "Interestingly, leptin levels were significantly lower in patients with dyskinesia." (PMID 37233709, 2023). "At the same time, the concentrations of leptin and melatonin in the patients without dyskinesia were significantly lower than in the controls." (PMID 37233709, 2023). "Melatonin, leptin, adiponectin, and resistin concentrations were measured in the blood serum of 20 PD patients without dyskinesia (ES), 24 PD patients with dyskinesia (AS), and 20 healthy volunteers as a control group (CG)." (PMID 37233709, 2023). "In the presented study, the serum levels of melatonin and leptin were statistically significantly lower in the PD patients without dyskinesia compared to the control group." (PMID 37233709, 2023).
E. coli infection (2 papers, 2018). "In Escherichia coli infection, leptin-deficiency impaired the phagocytosis by peritoneal macrophages; adequate supply of leptin inhibited the normal lymphocytes apoptosis by FAS-mediated pathway, and protected the starved mice from the loss of lymphocytes." (PMID 29868503, 2018). "E. coli infection caused an acute suppurative inflammation in the lung with increased lung index and serum TG and TC contents; elevated pulmonary tumor necrosis factor-α, interleukin (IL)-1β, IL-6, IL-8, and leptin levels; and oxidative stress in mice." (PMID 30250258, 2018).
eczema (2 papers, 2013 to 2020). "In the present study, we found an increased blood level of leptin in the adult AD of extrinsic origin, which lends credence to it mirroring the severity of eczema." (PMID 32899610, 2020). "Aside from the most hitherto time-tested and studied connection between the increase in blood leptin and AD symptoms, the present findings conversely show decreases in adiponectin and resistin as the presage of eczema severity." (PMID 32899610, 2020). "Thus, apart from the previously studied role of leptin in AD, this study directs attention to adiponectin and resistin as the candidate adipokines possibly involved in shaping eczema severity, which may help predict disease exacerbations and develop targeted therapeutic interventions." (PMID 32899610, 2020). "In this study, we addressed the contribution of adipokines to AD eczema based on the assessment of blood levels of adiponectin, resistin, leptin, lipocalin-2, and vaspin in adult non-obese patients suffering from chronic extrinsic childhood-onset AD." (PMID 32899610, 2020).
endometritis (2 papers, 2013 to 2019). An acute or chronic, usually bacterial infectious process affecting the endometrium. "Higher leptin levels in metritis and clinical endometritis cows in this study possibly explain reduced feed intake and loss in body condition." (PMID 24209779, 2013). "In this study the leptin concentrations were high in both metritis and clinical endometritis cows whereas IGF-1 concentrations were lower in other cow groups." (PMID 24209779, 2013). "Serum concentrations of leptin and IL-6 were lower in cows diagnosed with subclinical endometritis compared to those with metritis or clinical endometritis (P < 0.05)." (PMID 24209779, 2013). "Cows with subclinical endometritis had higher leptin and IL-6 concentrations compared to normal cows (P < 0.05), whereas IL-1β concentrations were higher in cows with any diagnosed uterine inflammatory conditions compared to normal cows (P < 0.05)." (PMID 24209779, 2013). "Cows with metritis or clinical endometritis had higher serum concentrations of adiponectin, leptin, TNF-alpha, IL-1beta and IL-6 compared to normal cows (P < 0.05)." (PMID 24209779, 2013). "In addition, cows with metritis or clinical endometritis show higher serum concentrations of leptin, adiponectin, IL-1β, IL-6and TNF-α." (PMID 31311492, 2019). "Furthermore, serum leptin, TNF-alpha, IL-1beta and IL-6 were higher in cows with subclinical endometritis compared to normal cows (P < 0.05), and insulin and IGF-1 concentrations were lower in cows with metritis or clinical endometritis." (PMID 24209779, 2013).
enteritis (2 papers, 2013 to 2023). Inflammation of the small intestine. "Furthermore we show for the first time that immune driven weight loss during enteritis results in reduced levels of the Th1 adipokine leptin augmenting a protective Th2 response during infection." (PMID 23349631, 2013). "Similarly, it was reported that leptin concentrations increased significantly in calves with enteritis, and it was concluded that this increase might be related to the role of leptin in repairing the damaged intestinal barrier and mucosal defence by stimulating the release of growth hormone." (PMID 37776262, 2023).
esophageal squamous cell carcinoma (2 papers, 2017 to 2023). Esophageal squamous cell carcinoma (ESCC) is a type of esophageal carcinoma (EC) that can affect any part of the esophagus, but is usually located in the upper or middle third. "Moreover, the levels of leptin were significantly correlated with lymph node involvement and advanced tumor stage esophageal squamous cell carcinoma." (PMID 37286356, 2023). "In this study, we aimed to examine the association of transcription factor 7-like 2, Leptin (LEP) and LEP receptor (LEPR) polymorphisms with esophageal squamous cell carcinoma (ESCC)." (PMID 29312594, 2017).
exocrine pancreatic insufficiency (2 papers, 2022 to 2025). Inability of the exocrine pancreas to produce and secrete an adequate amount of digestive enzymes into the small intestine. "Potential mechanisms for the increased risk of MetS include disruptions in leptin and adiponectin levels, early adiposity rebound, pancreatic insufficiency, poor dietary habits, sedentary lifestyle, and changes in the gut microbiome composition." (PMID 35073984, 2022).
gastric adenocarcinoma (2 papers, 2014 to 2019). "Lower LEP occurrence has also been reported with less differentiated gastric adenocarcinomas, and the authors suggested silencing of LEP/LEPR expression in advanced stages of cancers." (PMID 31592340, 2019).
gastric adenoma (2 papers, 2019 to 2020). A neoplastic polyp that arises from the stomach. "Gp130 is ubiquitously expressed and its mutant gp130757F mice developed inflammation-associated gastric adenoma because mutated gp130 cannot bind to SOCS3 with decreased in leptin expression in the gastric mucosa." (PMID 31141984, 2019).
Headache (2 papers, 2022). Cephalgia, or pain sensed in various parts of the head, not confined to the area of distribution of any nerve. "One experimental study published in 2017 found that the administration of insulin, glucagon, or leptin dramatically modulates the trigeminovascular system’s neuronal activity because of metabolic changes, which is a critical system in the pathogenesis of migraine headaches." (PMID 35627115, 2022).
hematoma (2 papers, 2022 to 2023). A hematoma is a collection of blood from a vascular structure into an extravascular space. "Surprisingly secretion of VEGF-A, VEGF-D, and Leptin was increased in the smokers’ hematomas, but VEGFR2/3, Angiopoietin 1/2 (Angpt1/2), and its receptor Tie2 were decreased drastically." (PMID 35621464, 2022).
Hirsutism (2 papers, 2012 to 2021). Abnormally increased hair growth referring to a male pattern of body hair (androgenic hair). "Our findingssupport the findings from other studies that foundno correlation between leptin and SHBG levelsin women with hirsutism and subjects withPCOS." (PMID 25493169, 2012).
Hypoinsulinemia (2 papers, 2006 to 2009). A decreased concentration of insulin in the blood. "Based on the recent reports showing that insulin increases leptin translation, hypoinsulinemia may affect the leptin turnover, which might contribute in part to the metabolic phenotypes in the KRAP−/− mice." (PMID 19156225, 2009).
hypovitaminosis (2 papers, 2019 to 2025). "Our data indicate that while being overweight did not significantly elevate the prevalence of hypovitaminosis, being obese, which is accompanied by higher leptin levels, was associated with a 12% increase." (PMID 40077674, 2025).
intellectual disabilities (2 papers, 2023 to 2025). "In this respect, the present study was designed to evaluate the levels mineral elements, and their correlation with oxidative stress markers and adiposity markers; leptin (L), adiponectin (A), and L/A ratio in adolescents with intellectual disabilities." (PMID 37730529, 2023). "In this respect, the present study was designed to evaluate the levels of mineral elements, and their correlation with oxidative stress markers and adiposity markers; leptin (L), adiponectin (A), and L/A ratio in adolescents with intellectual disabilities." (PMID 37730529, 2023).
intestinal cancer (2 papers, 2013 to 2014). "Various mouse models have highlighted the pivotal role of white adipose-derived leptin as an inflammatory cytokine that plays a critical role in the development of intestinal cancer." (PMID 23737651, 2013). "Surgical removal of the visceral fat mass significantly reduced the risk of intestinal cancer in female mice; however, it failed to increase the levels of adiponectin and reduce the level of glucose, leptin, chemokines, and total adiposity." (PMID 25402501, 2014). "Based on the literature, we propose that the lower white adipose tissue and lower circulating leptin levels may be responsible, in part, for the resistance to intestinal polyps formation observed in the two mouse models of intestinal cancer we previously tested." (PMID 23737651, 2013).
intestinal parasitic infection (2 papers, 2018 to 2025). "Each type of intestinal parasitic infection has been attributed to leptin concentration." (PMID 41239264, 2025). "An intestinal parasitic infection may influence the concentration of leptin in the blood." (PMID 41239264, 2025).
intestinal tumor (2 papers, 2013 to 2015). "In conclusion, we propose that the lower adipose and hence the lower leptin expression may attenuate the response to LPS treatment and may also be responsible for reduced intestinal tumor formation in NAG-1Tg/Lox mice." (PMID 23737651, 2013). "We propose that the reduced white adipose tissue and reduced leptin expression may be responsible, in part, for the reduced inflammatory response to LPS and the decrease in intestinal tumors observed in NAG-1Tg/Lox mice." (PMID 23737651, 2013).
keloid (2 papers, 2019 to 2022). An irregularly shaped, elevated mark on the skin caused by deposits of excessive amounts of collagen during wound healing. "Moreover, this study also found high local leptin levels in samples of keloid and hypertrophic skin lesions compared with normal skin samples." (PMID 30608959, 2019). "PCR showed that LEP, CIDEC and lncRNA HOTAIR showed increased expression (p < 0.05) in trunk keloid of trunk, while none showed statistical difference in ear keloid." (PMID 35677827, 2022).
Klebsiella pneumonia (2 papers, 2010 to 2020). An pneumonia caused by infection with Klebsiella. "Leptin universally decreased bacterial load and improved survival or immune response to infection with Mycobacterium tuberculosis, Klebsiella pneumonia, and Pneumococcal pneumonia." (PMID 33584724, 2020). "In leptin mutant ob/ob mice, bone marrow derived macrophages were shown to have decreased phagocytic ability in vitro, and ob/ob mice failed to clear infections such as Escherichia Coli and Klebsiella pneumonia in vivo." (PMID 33584724, 2020).
lichen planus (2 papers, 2014 to 2025). A chronic, recurrent, pruritic inflammatory disorder of unknown etiology that affects the skin and mucus membranes. "It supports the concept that lichen planus is a multisite mucocutaneous disease, and the consistent elevation of leptin levels in these patients may indicate a broader systemic alteration in immune regulation." (PMID 40764478, 2025).
lipoma (2 papers, 2018 to 2019). A benign, usually painless, well-circumscribed lipomatous tumor composed of adipose tissue. "Although there are no studies on gene expression in isolated cells some research groups investigated the differences in expression of ADIPOQ, LEP and PPARG, RUNX2 and BGLAP in lipoma tissue and compared it with normal adipose tissue." (PMID 30544806, 2018). "The quantification of the bound ORO staining unequivocally revealed that lipoma-derived ASCs have a significantly weaker capacity to differentiate into the adipogenic direction as confirmed by downregulated FABP4, PPARγ, and LEP expression compared to ASCs of RP and SC fat." (PMID 31640774, 2019).
lipomatosis (2 papers, 2021 to 2025). A neoplastic process characterized by diffuse overgrowth of mature adipose tissue. "Weight, BMI, blood pressure, gamma-GT, leptin, fasting insulin and C-peptide levels, fat mass percentage, and intra/total abdominal fat ratio were significantly higher in each lipomatosis group compared with the lean group." (PMID 34187516, 2021).
lysosomal storage disease (2 papers, 2019 to 2024). A metabolic disorder caused by mutations in proteins critical for lysosomal function, including lysosomal enzymes, lysosomal integral membrane proteins, and proteins involved in the post-translational modification and trafficking of lysosomal proteins. "Previous work on multiple preclinical lysosomal storage disease models, including MPS IIIB, found adipose deficiencies that correlated with reduced leptin levels indicative of altered energy balance." (PMID 38632525, 2024).
melancholic depression (2 papers, 2012 to 2016). "Higher levels of plasma leptin in patients with melancholic depression may have been caused by increased sympathetic tone." (PMID 22235252, 2012). "Catecholamines stimulate leptin secretion and CSF and plasma norepinephrine and epinephrine are increased in patients with melancholic depression." (PMID 22235252, 2012). "Women with melancholic depression had higher leptin levels compared to controls." (PMID 22235252, 2012). "Because leptin provides satiety cues to the brain, it may explain the lack of appetite in melancholic depression." (PMID 22235252, 2012).
metabolic acidosis (2 papers, 2015 to 2020). "Metabolic acidosis reduces the release of leptin from adipocytes and uremic factors of unclear origin reduce leptin gene expression in adipocytes probably as a negative feedback due to decreased elimination." (PMID 25944976, 2015).
mucinous adenocarcinoma (2 papers, 2010 to 2017). An invasive adenocarcinoma composed of malignant glandular cells which contain intracytoplasmic mucin. "Reasonable proportion of cases with low staining score was more prevalent in all subgroups of clinicopathological parameters except ER- PR+ HER2- hormone receptor phenotype and mucinous carcinoma which showed high level of leptin immunoreactivity." (PMID 29121911, 2017). "When compared control values, resistin levels were significantly higher in both patients' subgroups, while leptin levels were significantly lower only in the subgroup of patients with poorly differentiated (including the three patients with mucinous adenocarcinoma)." (PMID 21254741, 2010).
muscle atrophy (2 papers, 2010 to 2021). The loss of muscle tissue due to inactivity or disease. "Most obese people develop muscle atrophy in spite of exhibiting high leptin circulating concentrations, which may be explained by the leptin resistance present in these patients." (PMID 20671928, 2010).
myeloid malignancies (2 papers, 2022 to 2023). "Our findings indicated that hypermethylation of the LEP promoter is an early and frequent event in myeloid neoplasms and was associated with a worse prognosis in MDS." (PMID 37237325, 2023). "In summary, the data presented in this study indicate that hypermethylation of the LEP promoter is an early and frequent event in myeloid neoplasms and that it is associated with a worse prognosis in patients with MDS." (PMID 37237325, 2023). "In conclusion, hypermethylation of the LEP promoter is an early and frequent event in myeloid neoplasms and is associated with a worse prognosis." (PMID 37237325, 2023). "We investigated whether LEP promoter methylation is an early event in the development of myeloid neoplasms and whether it is associated with clinical outcome." (PMID 37237325, 2023). "The direct role of leptin in the initiation and progression of myeloid neoplasms is controversial and not fully understood." (PMID 37237325, 2023). "Further studies are needed to elucidate the association between myeloid neoplasms, LEP methylation, and circulating leptin levels." (PMID 37237325, 2023). "In conclusion, our results provide additional evidence for an interaction of nutritional homeostasis and control of myeloid malignancies after alloSCT and suggest a potential role of Leptin in this process." (PMID 35216457, 2022).
myoclonic epilepsy (2 papers, 2020 to 2025). A group of epilepsy syndromes in which myoclonic seizures are a prominent feature. "We describe a 5-year-old boy with an extremely rare phenotype involving severe progressive myoclonic epilepsy who received metreleptin (a recombinant analogue of leptin) to control metabolic abnormalities." (PMID 33099310, 2020). "It is unknown whether myoclonic epilepsy is related to altered BSLC2 expression in the brain; however, the improvement in myoclonic seizures following the introduction of metreleptin may suggest a contributory role for leptin deficiency in neurodegeneration." (PMID 40842493, 2025).
nasopharyngeal carcinoma (2 papers, 2022). A carcinoma arising from the nasopharyngeal epithelium. "However, the mechanisms underlying leptin-mediated regulation of lipid metabolism in nasopharyngeal carcinoma (NPC) remain incompletely understood." (PMID 35628510, 2022). "Leptin is important in physiological and pathological functions in various cancers, however, the significance and mechanisms of leptin in nasopharyngeal carcinoma remain ambiguous." (PMID 35778755, 2022).
neutropenia (2 papers, 2020 to 2023). A decrease in the number of neutrophils found in the blood. "PT children additionally showed neutropenia and decreased adiponectin, leptin, haematocrit, and haemoglobin." (PMID 33537270, 2020).
nicotine dependence (2 papers, 2020 to 2021). Physical and psychological dependence on nicotine. "Our findings further suggest a role for the leptin system in nicotine use, as we identified two LEP haplotypes to be associated with nicotine dependence and cigarette pack years in the African American group." (PMID 34421692, 2021). "Peptides that regulate appetite such as glucagon-like peptide 1 (GLP-1), ghrelin, leptin, peptide YY, and neuromedin U are expressed throughout the brain reward circuitry, providing strong evidence that food addiction and tobacco use disorder share overlapping gut–brain axis mechanisms." (PMID 33334010, 2020).